MMP13 (matrix metallopeptidase 13)
Diseases named in the same sentence as MMP13 in open-access papers (continued):
Sharing a sentence is not in itself a finding about the gene and the disease.
pulmonary fibrosis (20 papers, 2005 to 2025). Chronic progressive interstitial lung disorder characterized by the replacement of the lung tissue by connective tissue, leading to progressive dyspnea, respiratory failure, or right heart failure. "Others showed MMP13-deficient mice having delayed resolution of lung fibrosis through decreased collagenolytic activity." (PMID 34512395, 2021). "This suggests that Atp8b1 mutant mice may be susceptible to age-induced lung fibrosis mediated in part by MMP13." (PMID 27689529, 2016). "MMP13 has been shown to be downregulated in a model of pulmonary fibrosis induced in rats with paraquat and hyperoxia." (PMID 38576768, 2024). "In a model of radiation-induced pulmonary fibrosis, pro-fibrotic qualities of MMP13 were reported, too." (PMID 37207229, 2023). "In IPF rodent models, MMP13-deficiency demonstrated exacerbated inflammatory responses to lung injury and BLM-induced lung fibrosis, associated with increased leukocytic infiltration such as neutrophils and macrophages." (PMID 34512395, 2021). "While MMP12 functions in SSc-ILD have not been defined, MMP12 downregulated expression of collagenase MMP13 in a Schistosoma mansoni Th2-driven model of lung fibrosis, providing a crucial example of MMP-dependent regulation of other metalloproteinases." (PMID 34512395, 2021). "The downregulated genes contained some mediators related to pulmonary fibrosis, such as Mmp12 and Mmp13." (PMID 28936122, 2017). "MMP-12 reportedly has fibrotic activity in Fas-induced pulmonary fibrosis, and MMP-13 has shown similar activity in radiation-induced pulmonary fibrosis." (PMID 28936122, 2017). "Role of MMP13 was assessed employing the bleomycin model of lung fibrosis in MMP-13-/- versus wild-type mice." (PMID 24023851, 2013). "To further characterize the role of MMP-13 in lung fibrosis we employed the bleomycin model and observed an exaggerated early inflammation in the MMP-13-/- mice, which was attributable to a progressively increasing neutrophilic response." (PMID 24023851, 2013). "As compared with WT mice, MMP-13-/- mice exhibited augmented lung fibrosis 28days after bleomycin challenge, as evident from significantly increased collagen staining and hydroxyproline content." (PMID 24023851, 2013). "To further examine the role of MMP-13 in lung fibrosis we utilized the bleomycin model and characterized the inflammatory response in MMP-13-/- and WT mice at various time points after bleomycin challenge." (PMID 24023851, 2013). "Because mice lack the orthologue of human MMP-1 and in view of our clinical data, we further investigated the role of MMP-13 in the murine model of bleomycin-induced lung fibrosis." (PMID 24023851, 2013). "Mmp13, an interstitial collagenase, is considered a key activator in the cascade of proinflammatory reactions leading to pulmonary fibrosis." (PMID 21851604, 2011). "Elevated levels of MMP-7, MMP-9, and MMP-13 in severe COVID-19 cases are indicative of ongoing tissue remodeling and inflammation, which could contribute to lung fibrosis and other long-term complications." (PMID 40557167, 2025). "Based thereon, Mmp13-/- mice helped to analyze the dual role of MMP13 in liver and lung fibrosis." (PMID 37207229, 2023). "Our findings support the concept that CSP may facilitate the restoration of lung function by reducing the secretion of ECM to prevent expansion of lesions and inducing the expression of MMP13 to clear existing ECM deposits in pulmonary fibrosis." (PMID 35328736, 2022). "This suggests that MMP13 is associated with ECM remodeling and deficiency enhances lung fibrosis." (PMID 34512395, 2021). "Similarly, genes associated with ECM production and remodeling were significantly decreased with the loss of IL-31RA; these genes included MMP13 and TIMP1, as well as IL-6 which increased in wildtype mice during bleomycin-induced pulmonary fibrosis." (PMID 33815402, 2021).
pulmonary fibrosis (continued). "Also, in a murine model of bleomycin-induced lung fibrosis, MMP13−/− mice exhibited an increased inflammatory reaction and a greater extent of fibrosis compared with wild-type animals, but in a murine model of radiation-induced pulmonary fibrosis, MMP13 reduced pulmonary inflammation and fibrosis." (PMID 38576768, 2024). "We observed an exaggerated early inflammatory response and an augmented lung fibrosis in bleomycin-challenged MMP-13-/- versus wild-type mice, with elevated lung collagen content 28d after bleomycin challenge in the MMP-13-/- mice." (PMID 24023851, 2013). "Similarly, in an established model of lung fibrosis, RP-832c significantly decreased lung fibrosis and significantly decreased inflammatory cytokines TNF-α, IL-6, IL-10, IFN-γ, CXCL1/2, and fibrosis markers TGF-β1 and MMP-13." (PMID 37174654, 2023). "Furthermore, ELISA was used to detect pulmonary fibrosis markers COL-1, COL-3, WNT, Vimentin, β-Catenin, Fibronectin, α-SMA, N-Cadherin, E-Cadherin, TWIST, CTGF, FGF2, PDGF-α, MMP2, MMP8, MMP9, MMP13, TIMP1, TGF-β, Smad2, and Smad3 expression levels." (PMID 37812357, 2023). "Indeed, levels of MMP-2 and MMP-9 protein and MMP7 mRNA are elevated in the lungs of patients with human idiopathic pulmonary fibrosis (IPF) and MMP-13 expression is increased in the lungs of patients with chronic obstructive pulmonary disease (COPD)." (PMID 23593124, 2013). "Additional collagenases may exert a major role in lung homeostasis, possibly MMP-8 and MMP-13, which are also found to be induced in chronic obstructive pulmonary disease, or MMP-1, which is absent in fibroblast foci from idiopathic pulmonary fibrosis." (PMID 27066886, 2016). "Thirdly, our data suggest that MMP-13 plays a significant, if not pivotal, role in ECM remodeling in IPF, as this collagenase is dramatically upregulated in tissues from IPF patients and as excessive lung fibrosis is encountered in bleomycin challenged MMP-13-/-mice." (PMID 24023851, 2013).
tendinopathy (20 papers, 2011 to 2025). "MMP13 is the principal collagenase upregulated in tendinopathy of the human rotator cuff and has been implicated in the progression of partial tears into full thickness tears." (PMID 29023489, 2017). "MMP-13 has been associated with human tendinopathies, and this model shows that MMP-13 expression may be regulated by loading and resulting inflammatory cytokines." (PMID 32095779, 2019). "MMP13 staining revealed that significantly more MMP13 production was present in tendinopathy compared with healthy tendons, revealing a degenerative process." (PMID 35166070, 2022). "In horses with tendon disease, which had been treated by local MSC transplantation, a lower MMP13 activity in the MSC-treated group was associated with a better histological appearance and mechanical properties 6 months after treatment." (PMID 34884602, 2021). "In the early phase of tendinopathy, inflammation due to the response of the immune system causes damage to the tendon with induction of MMP-1 and MMP-13 expression as tendon catabolic markers." (PMID 32041254, 2020). "In agreement with our results, increases in MMP-13 (mRNA and protein) have been consistently reported in tendinopathy." (PMID 31068196, 2019). "Expression of MMP13 in human tendinopathy has been more variable, being increased in some cases but undetectable or unchanged in others." (PMID 25837713, 2015). "Previous studies have shown that MMP-13 increases in human tendinopathy, and increase in MMP-13 in the rat tendon may play a predominant role in matrix degradation following fatigue damage." (PMID 33603790, 2021). "Additionally, the collagenase MMP13 expression was significantly upregulated in the tendinopathy group compared to the intact tendons." (PMID 29385715, 2018). "The tendinopathy group showed significantly higher COL3 and MMP13 protein expression compared to the control group." (PMID 39442875, 2025). "The results of the Mmp3 and Mmp13 were similar, and the CEFFE-MNs group showed less positive staining than the tendinopathy and injection groups." (PMID 37600349, 2023). "However, MMP1, MMP13, MMP10, ADAMTS5, TIMP3, versican, aggrecan, biglycan, decorin, fibronectin, fibrillin and COMP showed an opposite response with strain compared to tendinopathy." (PMID 23830915, 2013). "The lack of expression of MMP1 and MMP13, which are known to be induced by inflammatory cytokines, further supports the proposal that pro-inflammatory cytokines do not play a major role in tendinopathy at this late stage of disease." (PMID 21539748, 2011). "Furthermore, the molecular docking results presented the stable and high-affinity binding of NGR1 to TNF-α, IL-6, MMP3, MMP9, and MMP13, indicating that NGR1 may exert its therapeutic effects on tendinopathy by modulating inflammatory responses and cellular and extracellular matrix metabolism." (PMID 40697661, 2025).
gastric cancer (19 papers, 2007 to 2024). A primary or metastatic malignant neoplasm involving the stomach. "In this study, our aim is to explore the diagnostic value of serum EFNA1 and MMP13 for gastric cancer." (PMID 38987376, 2024). "Collectively, these data reveal that RUNX2 enhances MGAT5 and MMP13 expression in gastric cancer cells and represents a biomarker and potential therapeutic target for gastric cancer therapy." (PMID 37256183, 2023). "MMP-1 and MMP-13 are both often overexpressed in epithelial cancers such as breast, prostate, and gastric cancer." (PMID 37055381, 2023). "In summary, we identify MGAT5 and MMP13 as novel RUNX2 targets with known metastatic potential in gastric cancer cells and tissue." (PMID 37256183, 2023). "In this study, it was uncovered that RUNX2 activates the transcription of MGAT5 and MMP13 which act to facilitate gastric cancer metastasis in vitro and in vivo." (PMID 37256183, 2023). "Consistent with previous studies, we observed high RUNX2 expression in gastric cancer cells which promoted MMP13 and MGAT5 expression." (PMID 37256183, 2023). "MGAT5, MMP13, and RUNX2 were significantly positively associated with each other in gastric cancer based on the GEPIA database." (PMID 37256183, 2023). "Together, these data revealed a role for RUNX2 in independently regulating the expression of MGAT5 and MMP13, the RUNX2/MGAT5/MMP13 positive axis in gastric cancer." (PMID 37256183, 2023). "This highlights RUNX2, MGAT5 and MMP13 as key biomarkers of metastatic gastric cancer and therapeutic targets for much-needed anti-gastric cancer drugs." (PMID 37256183, 2023). "H Huang’s study indicated dopamine D2 receptor suppresses invasion and migration of gastric cancer cells via inhibition of EGFR/AKT/MMP-13 pathway." (PMID 31164161, 2019). "Hence, our experiments were conducted to investigate the relationships among RUNX2, MGAT5 and MMP13 in gastric cancer." (PMID 37256183, 2023). "MMP13 is activated in gastric cancer and promotes the invasion of primary cancer cells." (PMID 37256183, 2023). "GOLM1 also upregulates MMP13 to promote the invasiveness of gastric cancer cells." (PMID 37256183, 2023). "We next examined whether the effects of RUNX2 on gastric cancer cells were mediated by the overexpression of MMP13 and MGAT5." (PMID 37256183, 2023). "SIRT1 could inhibit proliferation and metastasis of gastric cancer cells via the STAT3/MMP-13 signaling pathway." (PMID 36324577, 2022). "SIRT‐1 was shown to inhibit the proliferation and metastasis of gastric cancer cells through activating the STAT3/MMP‐13 signaling pathway by inducing phosphorylation/acetylation of matrix metalloproteinase 13 (MMP‐13) and STAT3 in both in vivo and in vitro models." (PMID 33133558, 2020). "Similarly, a previous study also reported that only the MEK1/2/ERK1/2 pathway was involved in EGF-induced MMP13 mRNA expression in gastric cancer cells." (PMID 31635309, 2019). "Analysis of the gastric cancer samples from the database revealed a significant positive correlation between MGAT5, MMP13, and RUNX2 expression." (PMID 37256183, 2023). "Due to the fact that both proteins are highly involved in gastric cancer progression and tumor invasion, thus, they proposed that COX-2 and MMP-13 expression can be used as a reference index for treatment strategy and a mean of disease prognosis." (PMID 35586209, 2022). "In gastric cancer and specimen with human esophageal carcinomas (ESCC) MMP-13 expression has been previously shown to contribute to malignant progression." (PMID 20946664, 2010). "Moreover, upregulated RUNX2 in gastric cancer also promotes gastric cancer progression through transcriptional activation of MGAT5 and MMP13." (PMID 38430423, 2024). "We further found that the effects of RUNX2 are mediated through the activation of MGAT5 and MMP13 both in vitro and in vivo, as their overexpression could compensate for RUNX2 depletion in gastric cancer cell lines and xenograft tumor models." (PMID 37256183, 2023).
gastric cancer (continued). "Hydrogen sulfide inhibits MGAT5 and displays antitumor efficacy in gastric cancer MMP13 has been shown to be upregulated in gastric cancer and can be inhibited by SIRT1 which modulates the STAT3/MMP13 axis to suppress cell proliferation and metastasis in gastric cancer." (PMID 37256183, 2023).
squamous cell carcinoma (19 papers, 2004 to 2025). A carcinoma arising from squamous epithelial cells. "An upregulated expression of MMP-1, MMP-2, and MMP-13 is associated with different malignant pathologies, such as squamous-cell carcinomas of the mouth." (PMID 39596178, 2024). "Suppression of MMP-13 expression by antisense ribozyme reduced squamous cell carcinoma growth and led to the inhibition of cell invasion and induction of cell apoptosis." (PMID 35805035, 2022). "MMP-13 is an additional protease that tends to be expressed during pathological situations and is particularly elevated by squamous cell carcinomas." (PMID 35936727, 2022). "It seems that TGF-β signalling regulates expression of MMP13 through SMAD-dependent pathway in squamous carcinoma cells, and in human gingival fibroblasts." (PMID 26395178, 2015). "Previous studies showed that MMP13 was induced by TGFβ in squamous carcinoma cells and in primary human gingival epithelial cells." (PMID 23762330, 2013). "In the cell line of human squamous carcinoma, vitamin D3 was found to reduce the production of both MMP-9 and MMP-13 mRNA and proteins in a manner that is dependent on the dosage applied." (PMID 37299440, 2023). "We have previously observed that Smad3 mediates the TGF-β-induced expression of MMP-13 and CTGF in human gingival fibroblasts and squamous carcinoma cells." (PMID 23468994, 2013). "The purpose of this study was to investigate MMP-13 and TIMP-1 expression in squamous cell carcinomas of the head and neck and to relate these levels of expression to histologic patterns of invasion." (PMID 15291964, 2004). "The expression of MMP-13 and TIMP-1 appears to play an important role in determining the invasive capacity of squamous cell carcinomas of the head and neck." (PMID 15291964, 2004). "However, it has been reported that Ephrin B2 promotes squamous cell carcinoma as well targeting MMD1 and MMP13." (PMID 31065284, 2019). "The expression of MMP-13 is seen in numerous cancer types, particularly carcinomas, and it has been suggested that MMP-13 could be an indicator for the invasive capacity of squamous cell carcinomas (SCCs)." (PMID 21326869, 2011).
breast tumors (18 papers, 2008 to 2025). "NRG‐mediated activation of HER receptors causes an increase in the production of metalloprotease 13 (MMP13, also termed collagenase‐3), which facilitates metastatic dissemination of breast tumors." (PMID 29032615, 2017). "Having established MMP13’s multifaceted roles in biomechanical modulation, we next dissect its cellular crosstalk within the breast tumour microenvironment." (PMID 40243781, 2025). "High MMP13 is commonly detected in breast tumours accompanied by a positive test for cancer cells in the lymph nodes as well as at the tumour–bone (TB) interface." (PMID 40243781, 2025). "For example, MMP13 was found to be induced in breast tumors, where its up-regulation at the interface between tumor tissue and bone matrix contributed to bone metastasis through promoting osteoclast differentiation." (PMID 35281094, 2022). "Earlier studies on human breast tumors had shown that MMP13 promotes formation of osteoclasts to trigger bone resorption and bone metastasis." (PMID 35281094, 2022). "Together, myoepithelial cell integrin β6 and fibronectin promote the activation of TGFβ signalling to induce the secretion of BM-degrading proteases MMP9 and MMP13 that facilitate breast tumour cell invasion." (PMID 36127361, 2022). "a Metastasis-free survival (MFS) curves for patients with breast tumors according to Low-MMP13 (n = 321) or High-MMP13 (n = 135) mRNA levels." (PMID 29996935, 2018). "b Metastasis-free survival (MFS) curves for breast tumor patients according to Low-MMP13 (n = 255) or High-MMP13 (n = 9) mRNA levels." (PMID 29996935, 2018). "A significant positive correlation between Pit-1 and both MMP-1 and MMP-13 was also found in human breast tumor datasets." (PMID 25527274, 2014). "Breast tumors containing MICs that were positive for Pit-1 and MMP13 (n = 24, 21.8%) had a high probability of recurrence (P = 0.010)." (PMID 25527274, 2014). "We further showed that Pit-1 positively correlated with MMP-1 and MMP-13 expression in 110 human breast tumors, and positive Pit-1 expression also correlated with positive expression of MMP-1 and MMP-13 in tumor cells and fibroblasts." (PMID 25527274, 2014). "This represents a direct experimental manipulation of the TACS stage of the tumor and therefore implicates stromal MMP13 as one driver of TACS evolution in breast tumors." (PMID 24010522, 2013). "MMP13 immunostaining of clinical primary breast tumors and experimental mice tumors revealed intra-tumoral and stromal expression in most tumors, and vasculature expression in all." (PMID 22253746, 2012). "MMP-13 released by breast tumour cells following stimulation with IL-8 or PTHrP played an amplifier role in the bone metastatic microenvironment by increasing and sustaining the erosion process of OCs." (PMID 22032644, 2011). "Singh and collaborators applied micro-dissection to breast tumour-bone interface and found that MMP-13, receptor activator of nuclear factor kappa-B ligand (RANKL) and integrin binding sialoprotein were among the most up-regulated genes." (PMID 22032644, 2011). "However, when the ECM is degraded and ECM remodelling is promoted in the tumour, MMP13 also plays a role in promoting breast tumour fibrosis in the long-term." (PMID 40243781, 2025). "Furthermore, invasion assays revealed that the knockdown of MMP13 in integrin β6-positive myoepithelial cell line led to a decrease in breast tumour cell invasion in vitro compared to control." (PMID 36127361, 2022). "Indeed, MMP13 is expressed in the endothelium surrounding breast tumors, suggesting a role in the modulation of extracellular matrix degradation and cell-matrix interactions involved in metastasis." (PMID 29996935, 2018). "MMP13, also called collagenase-3, was first cloned from a cDNA library derived from a breast tumor." (PMID 26966259, 2016). "In addition MMP-1 and MMP-13 positive expression in fibroblasts and tumor cells is positively correlated with high Pit-1 score values in human breast tumors." (PMID 25527274, 2014).